ZNF677 (zinc finger protein 677)
Diseases named in the same sentence as ZNF677 in open-access papers (continued):
Sharing a sentence is not in itself a finding about the gene and the disease.
cancer (7 papers, 2015 to 2022). A tumor composed of atypical neoplastic, often pleomorphic cells that invade other tissues. "Increased frequency of ZNF677 loss of expression was noted in cancer tissues when compared with control normal colorectal tissue." (PMID 34785764, 2021). "Further, both in vitro and in vivo data suggested that ZNF677 was involved in m6A modification‐regulated growth of cancer cells." (PMID 35678231, 2022). "ZNF677, which comprises C2H2-type ZFs and a KRAB domain and is a member of the KRAB-ZFP family, is located in the chromosomal region 19q13, where a frequent loss of heterozygosity occurs in cancer." (PMID 35164660, 2022). "Because of the significance of ZNF677 in cancer development, we hypothesized that it may play an important role in ccRCC tumorigenesis and metastasis." (PMID 35164660, 2022). "Sequence analysis demonstrated that the ZNF677 promoter contains a CpG Island, implying that CpG methylation may be involved in silencing its expression in cancer." (PMID 35164660, 2022). "Collectively, these results indicate that, like in other cancers, the low expression of ZNF677 in ccRCC may be due to its hypermethylation and can be considered as an adverse prognostic factor in ccRCC." (PMID 35164660, 2022). "Furthermore, IHC analysis revealed that ZNF677 protein levels were downregulated in cancer tissues." (PMID 35164660, 2022). "ZNF677, a member of the ZNF family, has recently been reported to be downregulated in several different types of cancer owing to promoter hypermethylation." (PMID 35164660, 2022). "ZNF677, which is often expressed in normal tissues, is decreased or absent in cancer tissues due to aberrant methylation." (PMID 35164660, 2022). "By comparing methylation values of these cell lines with ZNF677 mRNA expression values from the TCGA Cancer Cell Line Encyclopedia, a strong negative correlation between ZNF677 methylation and ZNF677 expression in these cell lines was observed (R = −0.889, p < 0.0001)." (PMID 25504438, 2015).
ZNF677 also shares sentences with these, for which no sentence is quoted: adenocarcinoma (1 paper); breast invasive carcinoma (1); Cirrhosis (1); colon cancer (1); colorectal cancer (1); endometrioid carcinomas (1); glioma (1); head and neck cancer (1); head and neck squamous cell carcinoma (1); laryngeal squamous cell carcinoma (1); liver cancer (1); ovarian carcinoma (1); pancreatic cancer (1); rectum adenocarcinoma (1); sclerosing cholangitis (1); squamous cell carcinoma (1); uterine corpus endometrioid carcinoma (1).